ENSG00000286001 (novel protein)
Gene: Protein-coding gene on chromosome 5 (218,298 to 314,955, forward strand). Ensembl gene ENSG00000286001.
Genetic constraint (gnomAD): Missense variants: 377 observed, 467.03 expected, observed/expected ratio (o/e) 0.81, 90% interval 0.74 to 0.88. Synonymous variants: 174 observed, 175.35 expected, observed/expected ratio (o/e) 0.99, 90% interval 0.88 to 1.12.